ENSG00000290893 (novel transcript)
Synonyms: ME4; PCDH-psi1; PCDHB17; PCDHB17P
Gene: Long non-coding RNA gene on chromosome 5 (141,155,996 to 141,159,061, forward strand). Ensembl gene ENSG00000290893.
Diseases named in the same sentence as ENSG00000290893 in open-access papers:
ENSG00000290893 is named in the same sentence as 2 diseases in open-access papers, as found by Europe PMC text mining. Sharing a sentence is not in itself a finding about the gene and the disease.
ENSG00000290893 shares sentences with these, for which no sentence is quoted: Sepsis (1 paper); tumours (1).